ACOT2 (acyl-CoA thioesterase 2)
Description:
Catalyzes the hydrolysis of acyl-CoAs into free fatty acids and coenzyme A (CoASH), regulating their respective intracellular levels. Displays higher activity toward long chain acyl CoAs (C14-C20). The enzyme is involved in enhancing the hepatic fatty acid oxidation in mitochondria (By similarity).
Synonyms: PTE2; PTE2A; Mte1; ZAP128; CTE-IA; CTE1A
Tractability: PROTAC: ubiquitination databases record sites on it; its protein half-life has been measured.
Target class: Enzyme; Hydrolase
Gene: Protein-coding gene on chromosome 14 (73,567,620 to 73,575,658, forward strand). Ensembl gene ENSG00000119673.
Subcellular location: Mitochondrion
Subcellular location (Human Protein Atlas): Mitochondria
Pathways (Reactome):
Disease: Maturation of DENV proteins
Metabolism: Mitochondrial Fatty Acid Beta-Oxidation
Metabolism of proteins: Mitochondrial protein degradation
Protein localization: Peroxisomal protein import
Gene Ontology:
Molecular function: fatty acyl-CoA hydrolase activity; protein binding; serine-type endopeptidase activity; long-chain fatty acyl-CoA hydrolase activity; medium-chain fatty acyl-CoA hydrolase activity; thiolester hydrolase activity
Biological process: acyl-CoA metabolic process; long-chain fatty acid metabolic process; very long-chain fatty acid metabolic process; protein maturation; fatty acid metabolic process; lipid metabolic process; monocarboxylic acid metabolic process
Cellular component: mitochondrion; cytosol; mitochondrial matrix; peroxisomal matrix; peroxisome
Genetic constraint (gnomAD): Loss-of-function variants: 15 observed, 19.39 expected, observed/expected ratio (o/e) 0.77, 90% interval 0.52 to 1.19. The upper end of that interval is the gene's LOEUF score, 1.19, which puts it in group 5 of 6, group 1 being the genes least tolerant of losing a copy. Missense variants: 426 observed, 441.73 expected, observed/expected ratio (o/e) 0.96, 90% interval 0.89 to 1.04. Synonymous variants: 224 observed, 194.5 expected, observed/expected ratio (o/e) 1.15, 90% interval 1.03 to 1.29.
Homologues: Orthologues: chimpanzee ACOT2 (94% identical), mouse Acot2 (70% identical), rat Acot2 (70% identical), rat Acot3 (68% identical), mouse Acot1 (66% identical), mouse Acot3 (66% identical), rat Acot1 (66% identical), mouse Acot5 (64% identical), rat Acot5 (64% identical), rat Acot5 (60% identical), tropical clawed frog acot2 (52% identical), tropical clawed frog jmjd7 (43% identical), and 7 more. Paralogues in human: ACOT1 (86% identical), ACOT4 (61% identical), ACOT6 (60% identical), BAAT (39% identical).
Diseases named in the same sentence as ACOT2 in open-access papers:
ACOT2 is named in the same sentence as 23 diseases in open-access papers, as found by Europe PMC text mining. Sharing a sentence is not in itself a finding about the gene and the disease. The quoted sentences say what the papers report.
steatosis (4 papers, 2016 to 2022). Increased lipid within the cytoplasm of cells. "Consistently, nine genes in the fatty acid metabolism, phospholipidosis and steatosis pathways including Acot2, Ugt2a1, Cd36 and Retn were upregulated in the cirrhotic liver post SPION injection accompanied with elevated Tgfb1 and sodium bile acid cotransporter (Slc10a1) of the cholestasis pathway." (PMID 27357559, 2016).
Obesity (3 papers, 2016 to 2025). Accumulation of substantial excess body fat. "In the diet-induced obesity rodent model, the expression of the ACOT2 protein in the heart and soleus muscle of the rats increased significantly in the high-fat diet group compared to the control diet." (PMID 41203872, 2025). "They showed that some lipid metabolism-related genes (i.e., Mod1, Cyp4a10, Hmgcs2, Acot1, Acot2, Pdk4, Acaa1b, Cpt1, Fabp1, and Acadl) were significantly up-regulated in the intestine of both A/J (obesity-resistant) and C57BL/6J (obesity-prone) mice fed with high fat diet." (PMID 26861690, 2016).
acute myeloid leukemia (2 papers, 2022 to 2025). Acute myeloid leukemia (AML) is a group of neoplasms arising from precursor cells committed to the myeloid cell-line differentiation. "Upregulation of ACOT2 has been reported in acute myeloid leukemia and breast cancer cells, where it is associated with poor survival outcomes." (PMID 40027135, 2025).
breast carcinoma (2 papers, 2010 to 2025). "To investigate whether a similar mechanism operates in breast cancer cells, we studied ACOT2 expression and intramitochondrial AA and lipooxygenase metabolites levels in the MDA-MB-231 and MCF-7 cell lines." (PMID 21085606, 2010). "We also found that ACOT2 is significantly up-regulated in highly aggressive breast cancer cells." (PMID 21085606, 2010). "We then investigated the role of ACSL4 and ACOT2 in the production of lipooxygenase metabolites by disrupting the expression of endogenous ACSL4 and ACOT2 in MDA-MB-231 breast cancer cells." (PMID 21085606, 2010). "In this study, we showed that ACSL4 acts in combination with ACOT2, LOX and COX-2 to generate an aggressive phenotype in breast cancer cells." (PMID 21085606, 2010).
diabetes (2 papers, 2012 to 2016). "Similarly, one study showed that, when the body contained higher fatty acids, as a result of diabetes or a high-fat diet, the expression of Acot1 and Acot2 was upregulated in liver, thereby promoting the catabolism of fatty acids." (PMID 27798284, 2016).
Hepatic steatosis (2 papers, 2024). Steatosis is a term used to denote lipid accumulation within hepatocytes. "Of those commonly upregulated, Acox1, Acot1, and Acot2 are all involved in lipid catabolism, lipid synthesis, liver inflammation, and hepatic steatosis." (PMID 38787127, 2024).
adrenocortical tumor (1 paper, 2020). "In addition, studies with Murine Y1 adrenocortical tumor cells have shown that the intracellular level of ARA in mitochondria is controlled by acyl-CoA synthetase long chain family member 4 (ACSL4) and acyl-CoA thioesterase 2 (ACOT2)." (PMID 32469895, 2020).
alcoholic steatohepatitis (1 paper, 2016). "In increased mRNAs, UCP2 was found to participate in hepatic simple steatosis; CIDEC was identified to promote alcoholic steatohepatitis in mice and humans and Acot2 was located at mitochondria matrix and associated with lipid metabolism." (PMID 27677588, 2016).
clear cell renal cell carcinoma (1 paper, 2023). "In clear cell renal cell carcinoma (ccRCC), the majority of ACOT members, including ACOT1, ACOT2, ACOT3, ACOT8 and ACOT11, are downregulated in the cancer samples." (PMID 37003979, 2023).
lung adenocarcinoma (1 paper, 2025). A carcinoma that arises from the lung and is characterized by the presence of malignant glandular epithelial cells. "ACOT2 is also one of the genes found to be altered in the metabolome-proteome profile of lung adenocarcinoma." (PMID 40027135, 2025).
virus infection (1 paper, 2024). "Therefore, we focused on investigating the role of ACOT2 in virus infection." (PMID 38112462, 2024).
cancer (4 papers, 2017 to 2025). A tumor composed of atypical neoplastic, often pleomorphic cells that invade other tissues. "ACOT2 is expressed in the liver, brain, and kidneys, localized within the mitochondria, and has been implicated in cancer development." (PMID 40027135, 2025). "Together, 183 proteins changed upon FGF19 treatment that were involved in different aspects of metabolism (e.g. Acot2, Acox1 and Acsl3) and 267 in cell survival/cancer (Col6a3." (PMID 28178326, 2017). "RCC tissues that successfully generated organoids highly expressed genes associated with stemness (WNT6/11, FZD8/9 and JAG2), cell matrix (MMP2, COL1A1), fatty metabolism (ACOT2, LIPE) and cancer development (TGFB1, SMAD6/7, EGF and FGF1)." (PMID 35802820, 2022).
infection (2 papers, 2022 to 2025). The state of being infected such as from the introduction of a foreign agent such as serum, vaccine, antigenic substance or organism. "As ACOT1 and ACOT2 are splice variants, these data suggest that functional differences and substrate specificities due to the location (cytosol and mitochondria, respectively) of these proteins may account for the differences in DENV2 infection phenotype." (PMID 35215835, 2022).
metabolic disease (2 papers, 2024 to 2025). A congenital disorder (due to inherited enzyme abnormality) or acquired (due to failure of a metabolically important organ) disorder resulting from an abnormal metabolic process. "Upregulation of ACOT2 in females, in conjunction with greater expression of UCP1, suggests that increased thermogenesis is acting as a protection against metabolic disease." (PMID 40181252, 2025).
ACOT2 also shares sentences with these, for which no sentence is quoted: brain disorder (1 paper); cholestasis (1); dyslipidemia (1); hepatocellular carcinoma (1); liver fibrosis (1); meningioma (1); neurological diseases (1); Type 1 diabetes (1); vitiligo (1).